SGK1 (serum/glucocorticoid regulated kinase 1)
Diseases named in the same sentence as SGK1 in open-access papers (continued):
Sharing a sentence is not in itself a finding about the gene and the disease.
Hepatic steatosis (4 papers, 2018 to 2025). Steatosis is a term used to denote lipid accumulation within hepatocytes. "In rodent studies, the introduction of a gain-of-function SGK1 mutation intensified both hepatic steatosis and fibrotic responses, while CYP11B2 deficiency protected against MASLD in animals with constitutive SGK1 activation." (PMID 40868048, 2025). "The findings from this study suggest that miR29c may provide geese tolerance against severe hepatic steatosis by modulating energy homeostasis and tissue growth and that its function is mediated by its target genes, Col3a1, Sgk1, and Insig1." (PMID 30400792, 2018). "The results suggested that Col3a1, Sgk1 and Insig1 were most likely to be the target genes of miR29c in the development of goose fatty liver, which was supported by the complete match of the 3’ UTR sequences of the genes to the core sequence of goose mature miR29c (note: Col3a1 had two matches)." (PMID 30400792, 2018). "Based on the functions of Col3a1, Sgk1 and Insig1 in cell growth, we conclude that miR29c may participate in tissue growth during the development of goose fatty liver, which enables the goose liver to tolerate severe steatosis at the end of the overfeeding period." (PMID 30400792, 2018).
mental disorder (4 papers, 2019 to 2024). A disease that has its basis in the disruption of mental process. "In this review article, we provide evidence from animal models for the potential role of SGK1 in the regulation of pathological pain caused by inflammation, nerve injury, psychiatric disorders, and chronic opioid exposure." (PMID 34093127, 2021). "Blocking the activation of Sgk1 can ameliorate allodynia induced by spinal nerve ligation in rats, as well as the development of pathological pain responses and pain caused by inflammation, nerve injury, psychiatric disorders, and chronic opioid exposure." (PMID 39355777, 2024). "Additionally, SGK1 plays a vital part in the regulation of neuronal activity, proliferation, and apoptosis and thus is a key determinant of susceptibility to mental illness." (PMID 31632443, 2019). "Given that the literatures remain limited, we focused on the role of SGK1 in inflammatory pain, neuropathic pain, psychiatric disorder-related pain, and opioid tolerance." (PMID 34093127, 2021). "In the context of these psychiatric disorders, the expression of SGK1 has been demonstrated to be increased in animals and humans." (PMID 34093127, 2021). "Animal experiments have shown that the mRNA level of SGK1 in the hippocampus of mice increased significantly under acute cold water swimming stress, suggesting that SGK1 is closely related to stress-related mental disorders." (PMID 31632443, 2019).
myocardial infarction (4 papers, 2013 to 2023). Gross necrosis of the myocardium, as a result of interruption of the blood supply to the area, as in coronary thrombosis. "Serum and glucocorticoid˗induced Kinase 1 (SGK1) is a transcriptionally induced Serine˗Threonine Kinase that is perhaps involved in ischemia/reperfusion (I/R) and myocardial infarction." (PMID 36865044, 2023). "On the other hand, SGK1 is a kinase that may be involved in I/R injury and myocardial infarction." (PMID 36865044, 2023). "A study using Sgk1 KO mouse hearts found that the lack of SGK1 impairs in vitro endothelial cell tube formation and reduces blood vessel production after myocardial infarction." (PMID 37371111, 2023). "Moreover, the lack of SGK1 led to defective endothelial cell (ECs) migration and tube formation in vitro, and increased scarring with decreased angiogenesis in vivo after myocardial infarct." (PMID 24265802, 2013).
osteoarthritis (4 papers, 2021 to 2024). A noninflammatory degenerative joint disease occurring chiefly in older persons, characterized by degeneration of the articular cartilage, hypertrophy of bone at the margins and changes in the synovial membrane. "A study found that SGK1 was upregulated in chondrocytes of osteoarthritis, and that SGK1 knockdown reduced catabolic and anabolic imbalances in chondrocytes." (PMID 39555740, 2024). "Expression levels of SGK1 were increased in diseased osteoarthritis cartilage, during which articular chondrocytes attain an aberrant hypertrophy-like state and lose phenotypic stability." (PMID 36457711, 2022). "A recent research has clarified that SGK1 is overexpressed in osteoarthritis cartilage." (PMID 35303795, 2022). "Treatment with each lead compound at a concentration of 2 μM reduced the staining intensity of collagen type X. Collectively, 16y, 16z, and 17a controlled osteoarthritis pathology, which was well-correlated with the SGK1 inhibitory activities of the lead compounds." (PMID 36457711, 2022).
osteoporosis (4 papers, 2020 to 2025). A condition of reduced bone mass, with decreased cortical thickness and a decrease in the number and size of the trabeculae of cancellous bone (but normal chemical composition), resulting in increased fracture incidence. "In addition to these functions, SGK1 plays a pivotal role in regulating the signaling pathways of bone metabolism in various types of osteoporosis, thereby affecting the function of bone-associated cells and the balance of bone remodeling." (PMID 40427579, 2025). "Increased bone resorption, caused by abnormal value-addition and differentiation of osteoclasts, is a primary factor in the development of osteoporosis, and the underlying cause may be related to the abnormal activation of SGK1." (PMID 40427579, 2025). "However, another goal for new osteoporosis drugs is to promote bone formation, and SGK1 was reported associated with osteoblastic formation according to previous studies." (PMID 36164394, 2022). "In this paper, we present a comprehensive review of the structure and activation mechanism of SGK1, its biological function, the role of SGK1 in different types of osteoporosis, and the inhibitors of SGK1." (PMID 40427579, 2025). "In studies of inflammatory factors, aberrant activation of SGK1 has been found to significantly accelerate the progression of osteoporosis through pro-inflammatory factor-mediated enhancement of bone resorption." (PMID 40427579, 2025). "Further exploration of the molecular mechanism of SGK1 in osteoporosis and its application in the treatment of specific types of osteoporosis, especially in postmenopausal osteoporosis, is needed in the future." (PMID 40427579, 2025). "In summary, further exploration of the function of SGK1 in osteoporosis and its potential as a therapeutic target is warranted." (PMID 40427579, 2025). "The augmentation of SGK1 activity expedited corticosterone/salt-induced renal injury, in addition to calcium and phosphorus metabolism abnormalities and osteoporosis." (PMID 40427579, 2025). "In light of these findings, it is important to thoroughly investigate the mechanism of action and therapeutic potential of SGK1 in osteoporosis." (PMID 40427579, 2025). "Collectively, our findings define a novel Sgk1-Stat3-Mycl-Ctsk signaling axis that contributes to osteoclastogenesis and suggest that Sgk1 inhibition represent a potential therapeutic strategy for osteoporosis." (PMID 41266497, 2025). "Recent studies have demonstrated the involvement of serum glucocorticoid-regulated protein kinase 1 (SGK1) in multiple signaling pathways that regulate bone metabolism and its significant role in the development of osteoporosis." (PMID 40427579, 2025). "Recent studies have demonstrated the pivotal role of SGK1 in the onset and progression of osteoporosis." (PMID 40427579, 2025). "Secondly, revealing the functional properties of SGK1 is expected to provide new targets for the development of novel therapeutic drugs against osteoporosis." (PMID 40427579, 2025). "In summary, SGK1 has been demonstrated to have complex bidirectional functional properties in the regulation of skeletal homeostasis in patients with senile osteoporosis." (PMID 40427579, 2025). "Therefore, it is of great significance to deeply explore the mechanism of SGK1 in osteoporosis and its therapeutic potential." (PMID 40427579, 2025). "Consequently, SGK1 emerges as a promising molecular target for therapeutic intervention in osteoporosis diseases." (PMID 40427579, 2025). "Consequently, the inhibition of the aberrant activation of SGK1 and the mitigation of the effects of inflammatory cytokines on bone metabolic homeostasis may emerge as a novel therapeutic approach for the treatment of senile osteoporosis in the future." (PMID 40427579, 2025).
osteoporosis (continued). "Furthermore, by thoroughly examining the interactions between SGK1 and other molecules or signaling pathways, potential biomarkers may be identified, thereby enhancing the efficacy of early screening and intervention for osteoporosis." (PMID 40427579, 2025). "Consequently, inhibition of SGK1 could be a potential target of osteoporosis." (PMID 36164394, 2022). "In addition, by exploring the interactions of SGK1 with other molecules and signaling pathways, this review may also provide clues for the discovery of potential biomarkers, which may, in turn, facilitate the optimization of osteoporosis screening and early intervention strategies." (PMID 40427579, 2025).
post-traumatic stress disorder (4 papers, 2015 to 2024). An anxiety disorder precipitated by an experience of intense fear or horror while exposed to a traumatic (especially life-threatening) event. "We found that the expression of a protein kinase involved in cellular responses to stress, known as serum and glucocorticoid regulated kinase 1 (SGK1), was decreased in the prefrontal cortex of subjects who had died with post-traumatic stress disorder." (PMID 26506154, 2015). "Work on rats and humans reveals a role for reduction in the levels of the stress-regulated protein kinase SGK1 in the development of post-traumatic stress disorder." (PMID 26506406, 2015). "Activity of the protein kinase SGK1 is reduced in the prefrontal cortex of individuals with post-traumatic stress disorder (PTSD), and SGK1 inhibition can cause PTSD-related behavioral changes in an animal model." (PMID 26506154, 2015).
Sepsis (4 papers, 2019 to 2023). Sepsis is defined as life-threatening organ dysfunction caused by a dysregulated host response to infection. "In conclusion, we used bioinformatics methods to screen three key macrophage-related genes, SGK1, DYSF and MSRB1, which have a good diagnostic effect on sepsis-induced ARDS." (PMID 37336980, 2023). "For example, melatonin attenuates sepsis‐induced lung injury by activating the serum and glucocorticoid regulated kinase 1 (SGK1)–NEDD4L pathway." (PMID 35355403, 2022). "The results of this study also suggest that melatonin attenuates sepsis-induced AFC reduction through up regulating ENaC expression via activation of SIRT1/SGK1/Nedd4-2 signaling pathway." (PMID 33362546, 2020). "Pre-treatment with melatonin obviously prevented the decrease of protein expression of SGK1 which was reduced by sepsis." (PMID 33362546, 2020). "We also found that melatonin could improve SGK1 expression and inhibit sepsis induced decrease of p-Nedd4-2 protein expression." (PMID 33362546, 2020). "We found that pretreatment with melatonin for 3 days before CLP could attenuated sepsis-induced acute lung injury through improvement of ENaC mediated alveolar fluid clearance which maybe through activation of SIRT1/SGK1/Nedd4-2 signaling pathway." (PMID 33362546, 2020). "Interestingly, several of the genes linked to glucocorticoid signaling (Arl4d, Cdkn1a, Ddit4, Fkbp5, Gjb6, Il6ra, Klf15, Nfkbia, Rhob, Sdc4, Sgk1, Sult1a1, Tob2, Wipf3) and apoptotic process were still upregulated 4 days post-sepsis." (PMID 31278440, 2019). "We found that melatonin attenuated sepsis induced lung injury, improved survival rate, enhanced alveolar fluid clearance, improved SIRT1 activity, increased protein expressions of SIRT1 and ENaC, and activated SGK1/Nedd4-2 pathway." (PMID 33362546, 2020).
squamous cell carcinoma (4 papers, 2012 to 2023). A carcinoma arising from squamous epithelial cells. "SGK1 variant 1: significant correlation with histolopathogical subtype (P = 0.017), with the highest expression in squamous cell carcinomas; significant correlation with the expression of the sum of the four SGK1 splicing variants (P = 4.7 × 10-6)." (PMID 22240294, 2012). "Another important finding relates to the observation of a reduction in the levels of both SGK-1 and pSGK-1 in the squamous cell carcinoma specimens compared with benign keratosis and dysplastic lesions, an effect more marked with respect to the former." (PMID 35048019, 2021). "On the other hand, the SGK-1 and pSGK-1 expressions decreased for squamous cell carcinoma specimens compared with benign keratosis or dysplastic specimens." (PMID 35048019, 2021). "If the role of SGK1 as a specific molecular marker for squamous cell carcinoma will be further validated, an inhibitor of SGK1 kinase activity would be highly appreciated in this NSCLC specific phenotype." (PMID 22240294, 2012). "This study tested the hypothesis that expression profiles of GILZ and SGK-1, along with the phosphorylated (active) form of SGK-1 (pSGK-1), are different in epithelial dysplasia than squamous cell carcinoma." (PMID 35048019, 2021). "Furthermore, the squamous cell carcinoma specimens displayed significantly reduced levels of SGK-1 and pSGK-1 compared with either benign keratosis or dysplasia specimens." (PMID 35048019, 2021). "Taking into account the previously published dependence of cisplatin treated squamous cell cancer on autophagy, it is tempting to speculate SGK-1 inhibition may play a role in this process, and increased cisplatin toxicity may result from a SGK-1 regulated attenuation of autophagic pathways." (PMID 25485633, 2014).
viral infection (4 papers, 2022 to 2025). "SGK1 is a host factor that is implicated in viral infection." (PMID 35438526, 2022). "Another type of STK (SGK1) is a host factor, which is involved in viral infection and promotes the replication of the influenza virus." (PMID 39576110, 2025). "Notably, the specific inclusion of cytotoxic-T-cell-specific genes (EOMES and SGK1) in the 20 gene signature differentiating critical patients further supports a role for inability to clear viral infection in COVID-19 severity." (PMID 36902333, 2023). "Recently, studies found that SGK1 has an important role in virus infection." (PMID 35438526, 2022).
adrenocortical carcinoma (3 papers, 2015 to 2022). "Decreased SGK1 expression was also observed in adrenocortical carcinoma, which is associated with adrenocorticotropic hormone (ACTH)-independent glucocorticoid secretion." (PMID 33542904, 2020).
allergic asthma (3 papers, 2016 to 2022). A asthma with a basis in a pathological type I hypersensitivity reaction. "In a mouse model of allergic asthma, SGK1 deficiency significantly reduces Th2 cell differentiation, while bronchoalveolar lavage fluid from Sgk1 gene knockout mice has lower concentrations of IL-4 and IgE, and mice were, therefore, resistant to Th2 cell-mediated allergic asthma." (PMID 35222400, 2022). "Furthermore, they found that T cell Sgk1−/− mice did not respond to allergen challenge in a murine model of allergic asthma." (PMID 36611927, 2022).
Arrhythmia (3 papers, 2016 to 2022). Any cardiac rhythm other than the normal sinus rhythm. "Activation of SGK1 in the heart causes a marked increase in both the peak and late sodium currents leading to prolongation of the action potential duration and an increased propensity to arrhythmia." (PMID 28336914, 2017). "Chronic SGK1 activation in the heart increases mortality caused by cardiac arrhythmias." (PMID 27517916, 2016). "Based on previous data that SGK1 regulates INa4, we sought to identify small molecule SGK1 inhibitors for use as pharmacological probes to validate SGK1 as a therapeutic target in the treatment of cardiac arrhythmias." (PMID 28336914, 2017). "Our results demonstrate proof of concept for SGK1 inhibition as a therapeutic target for cardiac arrhythmias and identify a small molecule lead, that with further medicinal chemistry can form the basis for novel and specific SGK1 inhibitors." (PMID 28336914, 2017). "Our data suggests that SGK1 inhibitors warrant further investigation in the treatment of cardiac arrhythmias." (PMID 28336914, 2017). "Our studies provide ‘proof-of-concept’ of SGK1 inhibition as a therapeutic target for treating cardiac arrhythmias." (PMID 28336914, 2017). "Here we show that SGK1 is an important regulator of INa, and that SGK1 inhibition represents a therapeutic strategy for the treatment of certain cardiac arrhythmias." (PMID 28336914, 2017). "The SGK1-dependent upregulation of Nav1.5 alters sodium flux, leading to arrhythmia and cardiomyopathy." (PMID 27517916, 2016).
atherosclerosis (3 papers, 2022 to 2025). A disease characterized by the build-up of fatty material and calcium deposition in the arterial wall resulting in partial or complete occlusion of the arterial lumen. "Considering that the phosphorylating change of WEE1 appears bigger than that of SGK1 and SGK1 has been reported to play a pivotal role in the development of atherosclerosis, we selected WEE1 for further investigation." (PMID 40202104, 2025).
Autoimmunity (3 papers, 2019 to 2022). The occurrence of an immune reaction against the organism's own cells or tissues. "Recently, additional mechanisms through which SGK1 aggravates autoimmunity have been elucidated and are linked to regulatory T cells (Tregs)." (PMID 36457711, 2022). "Indeed, the loss of SGK1 makes mice highly resistant to the development of autoimmunity, and SGK1 deficiency results in the inhibition of Th17 development and in the enhancement of Treg activity." (PMID 31060286, 2019). "This review provides a current understanding of SGK1, particularly in sodium transport, cancer progression, and autoimmunity." (PMID 36457711, 2022). "Our results were consistent with a previous report that activation of the β‐catenin‐SGK1‐Foxo axis was related to the function of interferon (IFN)‐γ+ Treg cells and autoimmunity, indicating that this observation may have broad relevance." (PMID 36514779, 2022).
Cerebral ischemia (3 papers, 2015 to 2024). Restriction of arterial blood supply to the brain associated with insufficient oxygenation to support the metabolic requirements of the tissue. "In hypoxic-ischemic brain injury, short-chain fatty acids were validated to inhibit inflammation produced by cerebral ischemia by reducing astrocyte activation through the SGK1/IL-6 signaling pathway." (PMID 39737082, 2024). "In summary, the presence of SGK1 plays a double-edged role for ischemic stroke, as it attenuates neuroinflammation on the one hand, while on the other hand it plays a negative role in CA-induced cerebral ischemia and the blood-brain barrier changes in stroke." (PMID 39737082, 2024).
endometriosis (3 papers, 2017 to 2023). The growth of functional endometrial tissue in anatomic sites outside the uterine body. "Dysregulated SGK1 is implicated in impaired endometrial receptivity, implantation failure, endometriosis and in fetal programming." (PMID 33195190, 2020). "Recently, SGK1 was found to be overexpressed in endometriosis associated with regulation of ectopic stromal cell survival." (PMID 28125717, 2017). "One of the identified genes was serum and glucocorticoid-regulated kinase (SGK1) which is overexpressed in the endometriosis tissue and contains an ERβ binding site in its promoter region." (PMID 37416064, 2023).